FASLG (Fas ligand)
Diseases named in the same sentence as FASLG in open-access papers (continued):
Sharing a sentence is not in itself a finding about the gene and the disease.
tumor (continued). "Upregulation of the Fas ligand is highly specific to blood vessels within the tumor, as it is often not seen in surrounding tissue." (PMID 35582566, 2019). "Besides, the expression of cytotoxicity-associated molecules, including granzyme, perforin, Fas/Fas Ligand and TRAIL, was higher in KLRG1+CD8 T cells than in KLRG1−CD8 T cells, suggesting that KLRG1+CD8 T cells might have higher cytotoxicity against tumor cells." (PMID 31664180, 2019). "TRAIL has historically been distinct from the Fas ligand and TNFα in terms of selective apoptosis induction in tumor cells and has a nearly non-existent systemic toxicity." (PMID 31412671, 2019). "In addition to free-floating cytokines, tumor cells in ascites are exposed to exosomes from other tumor cells, bearing proteins such as CD24 and the pro-apoptotic proteins Fas ligand and TRAIL." (PMID 31366178, 2019). "We subsequently examined whether the tumour killing activity of mIFN-DCs was dependent on TRAIL and Fas ligand." (PMID 28191816, 2017). "Following stimulation with VEGF, IL-10, or prostaglandin E2, tumor endothelial cells express Fas ligand (FasL), which kills activated CD8+ T lymphocytes but not regulatory T cells." (PMID 28665313, 2017). "Tumours treated with TH and MH showed no expression of FASLG and FADD (0% expression or positivity)." (PMID 28479926, 2017). "Clinically, mIFN-DCs may directly kill tumour cells that retain sensitivity to TRAIL and Fas ligand signalling." (PMID 28191816, 2017). "Furthermore, the expression of members of the tumour necrosis factor (TNF)-family like FAS ligand (FASL), TNF, and TNF-related apoptosis inducing ligand (TRAIL) are able to induce tumour-cell apoptosis upon formation of immune synapses." (PMID 27142426, 2016). "Indeed, Th1 cells can kill MHC-II+ tumor cells directly through perforine and granzyme, TNF-related apoptosis inducing ligand (TRAIL) receptor and Fas/Fas ligand pathways." (PMID 27686848, 2016). "Tumor intrinsic mechanism is achieved by immunosuppressive cytokines, vascular endothelial growth factor (VEGF), indoleamine 2,3-dioxygenase (IDO), programmed cell death ligand (PD-L), Fas ligand (Fas-L) and Treg." (PMID 27686848, 2016). "Earlier literature showed that DC possessed non-antibiotic properties including Fas/Fas Ligand (FasL)-mediated apoptosis against several tumor types in the concentration range of 10–40 μg/mL." (PMID 26205793, 2015). "Here, TNF-α, FasL (Fas ligand), and TRAIL (TNF-related apoptosis inducing ligand) are well known death ligands, and TRAIL, the most recently identified molecule among these ligands, is thought to be crucial for the tumor killing." (PMID 25875639, 2015). "Doxycycline (DC) has been shown to possess non-antibiotic properties including Fas/Fas Ligand (FasL)-mediated apoptosis against several tumor types in the concentration range of 10–40 μg/mL." (PMID 26205793, 2015). "Fas is not normally expressed on tumor cells and therefore NK cells aided Fas-dependent apoptosis upon binding with Fas ligand (FasL)-expressing NK cells." (PMID 24520300, 2014). "In addition, human GlyRS can be secreted from macrophages in response to Fas ligand released from tumor cells, and in turn participate in defense against ERK-activated tumor formation." (PMID 24743154, 2014). "Fas ligand (FasL) expressing CTL and NK cells can kill tumor cells expressing the Fas receptor." (PMID 22389673, 2012). "They confirmed the important role of IFN-γ for DTA-1-mediated tumor rejection and provided evidence that CD178/Fas Ligand, but not perforin is required for GITR-mediated effects on antitumor immunity." (PMID 20936139, 2010). "Tumor cells and CAFs produce immunosuppressive substances such as vascular endothelial growth factor (VEGF), IL-6, IL-10, transforming growth factor-β (TGF-β), soluble Fas ligand (Fas-L), and indolamine-2,3-dioxygenase (IDO)." (PMID 21048993, 2010).
tumor (continued). "Additionally, antigen-negative tumor cells, trigger apoptosis through death receptor ligands like Fas ligand (FasL)." (PMID 40230883, 2025). "NK cells mediate the tumor killing also triggering apoptotic pathways in tumor cells through the production of TNF-alpha or via direct cell–cell contact through activation of the Tumor necrosis factor (TNF)-related apoptosis-inducing ligand (TRAIL) and FAS ligand (FASL) pathways." (PMID 39981232, 2025). "Salmonella Typhimurium has been used in immunotherapies in murine trials, with significant tumor reduction, resulting from the local expression of bacteria or the expression of immune system-stimulating molecules on tumor cells IL-18, CCL21, LIGHT, or the Fas ligand." (PMID 39594765, 2024). "Moreover, VEGF promotes the expression of CLEVER-1, which correlates with Treg and M2 macrophage infiltration, and Fas-Ligand (FasL) specifically decreasing the number of tumor-infiltrating CTLs, without inducing Fas-mediated apoptosis in Tregs." (PMID 39580452, 2024). "Additionally, DNT cells have potent anti-tumor properties, reducing cancer cell proliferation and infiltration through mechanisms such as elevated production of interferon-γ (IFN-γ) and the expression of Fas ligand (FasL)." (PMID 39411714, 2024). "Additionally, CAR T cells can eliminate antigen-negative tumor cells within the antigen-positive environment via the Fas and Fas ligand (FasL) pathway." (PMID 38683232, 2024). "Furthermore, gene expression studies have demonstrated that expression of the Fas ligand (FasL) is higher in patients with BC than that in healthy individuals, regardless of the tumor grade or stage." (PMID 38107059, 2023). "Tumour cells are killed by CTLs, NK, NKT, γδT cells and macrophages, mechanisms including apoptosis inducing molecules ((Fas cell surface death receptor ligand(FASLG), TNF superfamily member 10 (TNFSF10)) and cytolytic molecules (granzyme, reactive oxygen species [ROS])." (PMID 35445563, 2022). "In contrast, both FASLG and IL2RB were specifically expressed in T cells, and were highly correlated with T cell marker genes, suggesting that these two genes might assist in maintaining normal function of T cell-mediated immune response in tumor tissues." (PMID 35707353, 2022). "Tumor cells are able to develop resistance to apoptosis by overexpressing BCL-2 and other anti-apoptosis molecules, or immune inhibitory receptor ligands such as programmed death ligand 1 (PD-L1), Fas ligand and tumor necrosis factor (TNF)-related apoptosis-inducing ligand (TRAIL)." (PMID 36498469, 2022). "Tumours treated with HSA showed no expression of FASLG and FADD (0% expression or positivity)." (PMID 35386216, 2022). "However, there are also some NRGs with CNV gain, such as FADD, FASLG, and no significantly difference in tumor and normal tissue." (PMID 36059470, 2022). "In tumor environment, DC-derived exosomes containing TNF, Fas ligand (FasL), and TNF-related apoptosis-inducing ligand (TRaIL) could lead to tumor cell apoptosis and activate natural killer cells via TNF superfamily ligands for enhanced tumor inhibition." (PMID 33868247, 2021). "We previously demonstrated that the OC tumor endothelium acted as a potent immune barrier by expressing the death mediator Fas ligand (FasL/CD95L) that preferentially killed CD8+ T cells, and such FasL expression was cooperatively induced by tumor-derived VEGF, IL-10, and PGE219." (PMID 33723260, 2021). "In addition to perforin/granzyme B-mediated toxicity, upregulation of Fas ligand (FasL) expression on CAR-T cells upon activation was shown to enhance their anticancer efficacy against bystander antigen-negative tumour cells." (PMID 32722109, 2020). "The migrated effector T cells to GvHD target organs and/or tumor sites exert their cytotoxic functions through direct cell contact-mediated or cell contact-independent cytokine-mediated cytotoxic pathways, including FAS ligand (CD95L)/FAS and perforin/granzyme pathways." (PMID 32560120, 2020).
tumor (continued). "CAR-T cells induce tumor cell apoptosis through different mechanisms than BH3 mimetics, including expression of cytolytic enzymes as perforin and granzyme, trimerization of Fas receptor by Fas ligand, release of effector cytokines, as well as secretion of extracellular vesicles." (PMID 33362794, 2020). "Also, tumor-derived VEGF, IL10, and PGE2 can all enhance the FASLG expression." (PMID 33381115, 2020). "Moreover, a mechanism regulating T cell infiltration at the tumor-endothelium interface was recently described, consisting in the selective expression of Fas ligand (FasL) by the tumor endothelium (but not in the normal endothelium)." (PMID 31783782, 2019). "Third, tumor ECs may also actively assist in the killing of Fas-expressing effector T cells, but not T regulatory cells (Tregs), by expressing Fas ligand (FasL)." (PMID 31440262, 2019). "Moreover, some cancer cells express FAS ligand (FasL) and the activation of FAS pathway may favor immune privilege to tumors by inducing apoptosis of anti-tumor lymphocytes." (PMID 29559981, 2018). "Fas ligand (FasL) is a mediator of T cell apoptosis; in the majority of tumors tested in a tissue array including a wide spectrum of tumor types, FasL was found to be selectively expressed on tumor endothelium, but not on the tumor cells themselves." (PMID 26442214, 2015). "Microglial cells appear to promote tumour growth directly (e.g. by producing growth factors) as well as indirectly by the secretion of immunosuppressive cytokines (e.g. TGF-β, IL-10) and the expression of molecules inducing apoptosis in lymphocytes (e.g. Fas ligand)." (PMID 23132370, 2013). "Presentation of tumor-specific antigens by antigen-presenting cells to CD8+ T cells results in release of different cytotoxic molecules (e.g., perforin, granzyme A, granzyme B, TNF-related apoptosis-inducing ligand (TRAIL), Fas ligand) which can target and kill dysplastic and tumor cells." (PMID 23109839, 2012). "Since shed membrane vesicles exhibit molecules with biologic activity (such as Fas ligand, mdr 1, CD44, and autoreactive tumour antigens), the ability of these shed membrane vesicles to modulate lymphocyte and monocyte functions have been analysed in several tumour models." (PMID 15655551, 2005). "Recent studies have shown that tumour cells can assume characteristics similar to those of immune-privileged tissues such as the low expression or absence of surface Fas receptor (Fas) and the expression of Fas ligand (FasL)." (PMID 12610520, 2003). "Similar to effector T cells, CAR-T cells could also mediate tumor killing in several manners, including secretion of cytotoxic granules containing perforin and granzymes, production of pro-inflammatory cytokines like IFN-γ and TNF-α, and activation of Fas/Fas ligand (Fas/FasL) pathway." (PMID 36891310, 2023). "However, TGF-β, produced by tumor cells acts as an immunosuppressive factor that helps cancer cells escape from the immune response by inhibiting the expression of molecules involved in the CTL-mediated tumor cytotoxicity such as perforin, granzyme A, granzyme B, Fas ligand, and IFN-γ." (PMID 37958417, 2023). "In addition, activated NK cells may also induce the apoptosis of tumor cells by releasing TNFα or through cell-to-cell contacts that activate the tumor necrosis factor (TNF)α–related apoptosis-inducing ligand (TRAIL) and FAS-ligand (FAS-L) pathways." (PMID 34069127, 2021). "Fas ligand (FasL)-induced apoptosis is an immune regulatory mechanism, and DC-derived EVs with TNF, FasL and TNF related apoptosis inducing ligand (TRAIL) can activate natural killer cells, and induce tumor cell apoptosis, and could also play a role in systemic inflammation." (PMID 28491866, 2017).
tumor (continued). "The difference in the efficiency towards the different CD30+ cell lines might be due to the various anti-tumor mechanisms, such as effector to target-cell contact, signaling and tumor apoptosis via the Fas ligand of CIK cells, which might be not as effective for each cell line." (PMID 27376285, 2016). "We observed significantly increased gene scores for FAS, FASLG and TNFSF10 in C11_CD8 compared with the nondysfunctional/effector tumor-infiltrating CD8+ T cells and earlier dysfunction fates." (PMID 35668194, 2022). "Even though MOPC315 cells showed a modest susceptibility to Fas-mediated killing by co-incubation with the Fas ligand-expressing cell line L5178Y-FasL, c-FLIP-L-overexpressing tumor cells showed no resistance toward killing by macrophages." (PMID 30083157, 2018). "Toxicity towards hepatocytes and non-transformed cells was seen also for treatments with Fas ligand/CD95L; nevertheless, a novel preparation is being tested for safety and activity on different tumor types." (PMID 24920406, 2014). "Moreover, antigen-independent cytolysis can be induced by CAR T cells via upregulation of Fas ligand, resulting in subsequent cytolytic interactions with CAR-antigen negative, Fas-expressing tumor cells." (PMID 32357417, 2020).
cancer (645 papers, 1999 to 2026). A tumor composed of atypical neoplastic, often pleomorphic cells that invade other tissues. "Using cell staining, we noticed that cancer cells were more susceptible to death at the intermediate concentrations of FASLG (10 and 30 ng/ml)." (PMID 39068622, 2024). "This can explain the effect observed in studies on different cancer types that found an association between soluble FASLG and poor prognosis." (PMID 38067332, 2023). "Increased expression of FASLG is associated with sensitivity of cancer cells to oxaliplatin, ribociclib (LEE-011) and palbociclib." (PMID 35165523, 2022). "FAS and FASLG genes have a crucial role in apoptosis processes and their polymorphisms have been reported to affect the risk of cancer, including SPCs." (PMID 34078296, 2021). "Using linear regression models adjusted for age, urinary osmolality, and urinary leukocytes, we identified associations between B-As and four putative cancer-related proteins: FASLG, SEZ6L, LYPD3, and TFPI2." (PMID 33381488, 2020). "Using multiplex proteomic methods in urine samples, we identified four putative cancer-related proteins (FASLG, SEZ6L, LYPD3, and TFPI2) associated with arsenic exposure in women living around Lake Poopó, Bolivia." (PMID 33381488, 2020). "The majority of human cancers were found to overexpress the gene encoding Fas-ligand (FasL) relative to normal tissues." (PMID 29996914, 2018). "In the classical pathway involving Factor Associated Suicide/Fas ligand (Fas/FasL) signaling, the Fas receptor interacts with FasL, which is predominantly secreted by activated T cells, natural killer (NK) cells, and specific malignant tumor cells, via its extracellular domain." (PMID 40927684, 2025). "Furthermore, they can prevent the activation of the protein Fas ligand (FasL), which causes cancer cells to undergo apoptosis and spread to the brain." (PMID 40234973, 2025). "Previous studies have found an association between FASLG expression and anti-cancer activity." (PMID 38067332, 2023). "Survival analysis showed that CNVs of TNF in 22 cancer types, TLR3 in 10 cancer types, RIPK1 in 9 cancer types, FAS in 8 cancer types, FADD in 8 cancer types, RIPK3 in 7 cancer types, MLKL in 6 cancer types, and FASLG in 5 cancer types were significantly associated with overall prognosis." (PMID 35748782, 2022). "Recently, FAS and FASLG polymorphisms have been reported in various cancers and alopecia." (PMID 29950587, 2018). "Furthermore, FASLG is closely associated with apoptosis in a large number of cancers." (PMID 34889164, 2021). "Upon interaction with cancer cells, γδ T cells can express Fas ligand (FASL) and TNF-related apoptosis-inducing ligand (TRAIL), which, upon binding to their respective receptors, Fas (CD95) and TRAIL-R1/R2, activate death pathways in target cells." (PMID 40276509, 2025). "Overexpression of miR-21 suppresses FASLG expression, reducing apoptosis and contributing to cancer progression." (PMID 40971385, 2025). "MRTX1133, via Fas ligand on CD8+ T cells activated Fas-mediated apoptosis of cancer cells and led to a significant increase in the number of CD3+ T cells, CD8+ T cells, and CD19+ cells, and a decrease in CD11b+ myeloid infiltration." (PMID 40641916, 2025). "This study concluded that PD-L1 intracellular signaling conferred resistance to cancer cells against pro-apoptotic stimuli, including first apoptosis signal receptor (Fas)-Fas ligand (FasL) interactions, among others." (PMID 40427133, 2025). "For example, neutrophils with enhanced expression of TRAIL and Fas ligand (FasL) can induce programmed cell death or apoptosis through direct contact with cancer cells." (PMID 40979214, 2025). "Glycolytic reprogramming in cancer cells further contributes to immune escape by inducing Fas ligand (FasL) expression, which triggers activation-induced cell death (AICD) in T cells via TCR restimulation." (PMID 40868256, 2025).